EGFR (epidermal growth factor receptor)
Diseases named in the same sentence as EGFR in open-access papers (continued):
Sharing a sentence is not in itself a finding about the gene and the disease.
pulmonary hypertension (10 papers, 2011 to 2024). Increased pressure within the pulmonary circulation due to lung or heart disorder. "Studies have also indicated that, age > 50 years, hydrothorax, pulmonary arterial hypertension, and epidermal growth factor receptor <30 mL/min/1.73 m2 predict poor patient prognosis." (PMID 39109224, 2024). "For example, cardiotoxicity caused by ALK, ROS1, EGFR-TKIs; aortic coarctation caused by VEGF-TKI; pulmonary hypertension caused by ALK-TKI, interstitial pneumonia caused by EGFR/ALK TKIs, infection caused by BTK inhibitors and other adverse reactions." (PMID 36761953, 2023). "EGFR immunoreactivity was focal and weak in the pulmonary hypertension groups and was observed mostly in media and intima of the pulmonary vessels." (PMID 21492463, 2011). "In pulmonary hypertension, a role of PDGFR-β and EGFR in the improvement of hemodynamic function has been suggested in animal models." (PMID 21492463, 2011). "Our patient was diagnosed after development of severe pulmonary hypertension and her immune-histochemical staining was negative for EGFR, ER, and PR which added to her dismal outcome." (PMID 25478243, 2014).
adrenocortical carcinoma (9 papers, 2006 to 2025). "Receptors of the EGFR/ErbB family have been detected in the nuclei of various human cancer types such as sarcoma, adrenocortical carcinoma, uterine cervix lesions, mouth cancer, and breast cancer." (PMID 17049074, 2006).
alcoholism (9 papers, 2015 to 2025). "For example, we demonstrate that MEK inhibitors amplify the viability effect of the clinically used anti‐alcoholism drug disulfiram and show that the EGFR inhibitor tyrphostin AG555 has off‐target activity on the proteasome." (PMID 26700849, 2015). "Hypomagnesaemia is associated with malnutrition, intestinal malabsorption, diarrhoea, alcoholism, cisplatin chemotherapy, EGFR inhibitors, diuretics, inherited renal tubular defects, interstitial nephritis, aminoglycosides and hyperaldosteronism." (PMID 25138239, 2015).
Barrett esophagus (9 papers, 2010 to 2025). Esophageal lesion lined with columnar metaplastic epithelium which is flat or villiform. "In addition, the inactivation of EGFR by deoxycholic acid activated an intestine-specific cascade typical for Barrett's metaplasia." (PMID 36092955, 2022). "It is therefore interesting to note that we previously showed co-upregulation of ERK signalling and ETV4 expression in OAC and that genes encoding members of the RAS/ERK signalling cascade such as EGFR and KRAS are often amplified in the transition from Barrett’s oesophagus to adenocarcinoma." (PMID 28859074, 2017).
cholesteatoma (9 papers, 2013 to 2023). A pathologic process characterized by the proliferation of keratinizing squamous epithelium resulting in the accumulation of keratin and cells in the middle ear and/or mastoid. "A promising candidate marker for intraoperative localization of cholesteatoma is EGFR, since skin cysts are known to overexpress this marker compared to adjacent tissues of the head and neck." (PMID 36402793, 2022). "Conventional fluorescent immunohistochemistry staining using Cet-AF647 in fixed tissues demonstrates the expected distribution for EGFR antibody affinity as a positive control for human skin, cholesteatoma sac and middle ear mucosa." (PMID 36402793, 2022). "Immunohistochemistry of cholesteatoma tissues and retroauricular skin samples revealed strong expression of both EGFR and ErbB4 by the epithelial cells of both cholesteatoma and retroauricular skin." (PMID 23826119, 2013). "In cholesteatoma epithelium, a significant positive correlation was observed between p-EGFR and PCNA expression and between the expressions of p-Akt and PCNA, cyclinD1, and PCNA, respectively (P < 0.01)." (PMID 24311896, 2013). "Our results are consistent with these findings and demonstrate for the first time that EGFR/PI3K/Akt/cyclinD1 signaling pathway is active in cholesteatoma epithelium and involved in EGF-induced cell proliferation of EACKs." (PMID 24311896, 2013). "Recent studies have shown that EGFR immunoreactivity was significantly increased in cholesteatoma epithelium when compared with normal EAC epithelium." (PMID 24311896, 2013). "Previous studies have shown the expression of EGF and increased expression of EGF receptors (EGFR) in cholesteatoma." (PMID 23852020, 2013). "Cholesteatomas exhibit increased expression of epidermal growth factor receptor (EGFR), transforming growth factor-α (TGF-α), c-jun, and c-myc, accompanied by a significant upregulation of inflammation-related genes and downregulation of several tumor suppressor genes." (PMID 29317713, 2018). "Moreover, in cholesteatoma epithelium, we demonstrated that a significant positive correlation was observed between p-EGFR and PCNA expression and between the expression levels of p-Akt and PCNA, cyclinD1 and PCNA, respectively." (PMID 24311896, 2013). "In the current study, we analyzed the protein expression of three key components of the EGFR/PI3K/Akt/cyclinD1 pathway and demonstrated that protein expression of p-EGFR, and p-Akt, cyclinD1 in cholesteatoma epithelium was significantly increased when compared with normal EAC epithelium." (PMID 24311896, 2013). "Overexpression of EGFR and TGF-α has also been detected in cholesteatomas, indicating that the dysregulation of these genes may be associated with the initiation and progression of cholesteatomas." (PMID 25866816, 2015). "Firstly, although several past studies on cholesteatoma explored not only MMP2 but also IL-6, other MMPs, TREM-2, and EGFR, this study focused only on the expression of MMP2 mRNA." (PMID 33778077, 2021). "The expressions of p-EGFR, p-Akt, cyclinD1, and PCNA in cholesteatoma epithelium were significantly increased when compared with those of control subjects." (PMID 24311896, 2013). "The positive rate of p-EGFR, p-Akt, cyclinD1, and PCNA expression was significantly increased in cholesteatoma epithelium (65.0%, 72.5%, 62.5%, and 80.0%, resp)." (PMID 24311896, 2013). "Candidate-gene approaches (analysing molecules known to regulate pathways altered in cholesteatoma) have found increased expression of interleukin-1 (IL1), tumor necrosis factor-alpha (TNFα), and defects in the regulation of epidermal growth factor receptor (EGFR)." (PMID 36920900, 2023). "In summary, our studies demonstrate that the EGFR/PI3K/Akt/cyclinD1 signaling pathway is active in cholesteatoma and may play a crucial role in cholesteatoma epithelial hyperproliferation." (PMID 24311896, 2013).
cholesteatoma (continued). "Taken together, our data suggest that the EGFR/PI3K/Akt/cyclinD1 signaling pathway is active in cholesteatoma and may play a crucial role in cholesteatoma epithelial hyper-proliferation." (PMID 24311896, 2013). "We examined the expressions of phosphorylated EGF receptor (p-EGFR), phosphorylated Akt (p-Akt), cyclinD1, and proliferating cell nuclear antigen (PCNA) in 40 cholesteatoma samples and 20 samples of normal external auditory canal (EAC) epithelium by immunohistochemical method." (PMID 24311896, 2013).
congestive heart failure (9 papers, 2013 to 2023). Failure of the heart to pump a sufficient amount of blood to meet the needs of the body tissues, resulting in tissue congestion and edema. "Triple-antibody therapy targeting HER1-2-3, although previously demonstrated strong tumor control, raises the risk of potential long-term adverse effects such as chronic heart failure, given that EGFR, HER2 and HER3 are expressed in myocardium." (PMID 35347108, 2022). "In EGFR(+) group, factors selected were age, gender, congestive heart failure, renal disease, number of lymph node examined, tumor stage, surgical intervention, radiotherapy, first-line chemotherapy, ECOG performance status, malignant pleural effusion, and smoking." (PMID 31419239, 2019). "However, the overall balance of cardiac transcript alterations and their ultimate contribution to βAR-mediated EGFR-dependent cardioprotective effects in chronic heart failure models remains to be tested." (PMID 24901703, 2014).
glomerulonephritis (9 papers, 2012 to 2024). A renal disorder characterized by damage in the glomeruli. "Summary of selected studies highlighting the role of EGFR signalling in glomerulonephritis and associated pathologies." (PMID 39234105, 2024). "In HB-EGF-deficient mice with progressive glomerulonephritis, inflammatory renal infiltration and albuminuria were lower which was ascribed to EGFR pathway inhibition in podocytes." (PMID 26064952, 2015). "Since podocyte EGFR/STAT3 signaling is known to mediate the development of anti-GBM glomerulonephritis, we investigated the effect of glucocorticoids on EGFR/STAT3 signaling in podocytes." (PMID 35223886, 2022). "Taken together, rTMD1 is promising in the treatment of EGFR-mediated inflammation, including glomerulonephritis." (PMID 22449172, 2012). "In addition, activation of epidermal growth factor receptor (EGFR) was demonstrated in glomerular disease, especially rapidly progressive glomerulonephritis." (PMID 22449172, 2012). "In another study, deletion of signal transducer and activator of transcription 3 (STAT3) a downstream target of activated EGFR, in podocytes was found to markedly reduce crescent formation in the mouse model of anti-GBM glomerulonephritis." (PMID 35223886, 2022). "We found aberrant activation of EGFR and STAT3 in podocytes of the experimental glomerulonephritis model, as shown by the striking staining of phosphorylated EGFR and STAT3, which were not present in healthy controls and eliminated in the NTS rats with MP treatment." (PMID 35223886, 2022). "In a rat model of anti-GBM glomerulonephritis, glucocorticoids treatment significantly attenuated the proteinuria, crescent formation, parietal epithelial cell (PEC) activation and proliferation, accompanied by elimination of podocyte EGFR/STAT3 signaling activation." (PMID 35223886, 2022).
Hypokalemia (9 papers, 2017 to 2025). An abnormally decreased potassium concentration in the blood. "Hypokalemia and asthenia tended to occur more frequently when an anti-EGFR agent was added to chemotherapy." (PMID 29228748, 2017). "Analysis based on the types of targeted therapies indicated the pooled incidence of hypokalemia varied from 1% (95% CI: 0%, 3%) in the EGFR inhibitors group to 26% (95% CI: 23%, 29%) in the combination of VEGF and EGFR inhibitors and chemotherapy group (heterogeneity between groups: p < 0.01)." (PMID 40183088, 2025).
Hyponatremia (9 papers, 2014 to 2025). An abnormally decreased sodium concentration in the blood. "The highest incidence of severe hyponatraemia (<120 mmol/l) was reported with cetuximab (34.8%), while the lowest incidence with gefitinib, an EGFR inhibitor (1.0%)." (PMID 32509580, 2020). "The incidence of high-grade hyponatraemia was 7.2 [95% CI 5.5 to 8.8] with the inhibitors of angiogenesis and 8.8 [95% CI 6.9 11.0] with anti-EGFR TKIs or mAbs." (PMID 27167519, 2016). "Univariate analysis demonstrated that male gender, PS ≥2, tumor stage IV, non-adenocarcinoma histology, wild-type EGFR status and hyponatremia were significantly associated with worse OS." (PMID 27863417, 2017). "Indeed, the RR of developing high-grade hyponatraemia with anti-angiogenic agents was 2.69 compared to anti-EGFR TKIs or mAbs." (PMID 27167519, 2016). "Moreover, the RR of high-grade hyponatraemia with inhibitors of angiogenesis was 2.69 (95% CI 1.62 to 4.48) compared to anti-EGFR TKIs or mAbs (1.12 95% CI 0.81 to 1.53)." (PMID 27167519, 2016). "Interestingly, in NSCLC patients treated with the EGFR inhibitor erlotinib a multivariate analysis revealed that hyponatremia was an independent predictive factor of non-response to therapy, in the same way as a poor performance status and the absence of EGFR mutations in the tumoral tissue." (PMID 36831539, 2023). "This may occur either through SIADH resulting from epidermal growth factor receptor (EGFR) pathway blockade or as a consequence of one of its most common adverse effects, such as diarrhea, which can also lead to hyponatremia, as previously discussed." (PMID 41010788, 2025).
kidney tumors (9 papers, 2005 to 2021). "Increased EGFR activity is observed in renal tumors from BHD patients and in a murine model of BHD-related kidney cancer." (PMID 33981707, 2021). "Inhibition of EGFR with afatinib decreases tumor growth in mice, suggesting an important contribution of EGFR signaling to the progression of BHD-associated renal tumors." (PMID 33981707, 2021). "A key finding is recurrent mutation of EGFR in CMN by internal tandem duplication of the kinase domain, thus delineating CMN from other childhood renal tumors." (PMID 29915264, 2018). "To validate and extend our findings, we screened IFS and a range of childhood renal tumors for EGFR-ITD, BRAF-ID, and ETV6-NTRK3 using PCR." (PMID 29915264, 2018). "Pancreatic, colon, lung, ovarian and kidney tumors show aberrant epidermal growth factor receptor (EGFR) activation and MAP kinase signaling." (PMID 29285250, 2017). "While targeting TGFα with antibodies that block its interaction with the EGFR may inhibit tumor progression, our findings on the molecular forms of TGFα expressed in kidney tumors open a new therapeutic scenario." (PMID 34399807, 2021). "Interestingly, it has been shown that Notch signaling is dependent on mTOR in lung and kidney tumor cells, indicating the existence of a positive feedback loop between Notch and EGFR signaling." (PMID 27118928, 2016). "None of the IFS cases, nor other childhood kidney tumors, harbored EGFR-ITD." (PMID 29915264, 2018).
leiomyoma (9 papers, 2012 to 2026). A well-circumscribed benign smooth muscle neoplasm characterized by the presence of spindle cells with cigar-shaped nuclei, interlacing fascicles, and a whorled pattern. "EGFR was described as immunolocalized of its proteins in the cytoplasm of smooth-muscle cells in the leiomyoma and matched myometrium." (PMID 30200635, 2018). "Both epidermal growth factor (EGF) and its receptor (EGFR) have been shown to be expressed in both myometrial and leiomyoma tissues during the secretory phase of the menstrual cycle but EGF mRNA was higher in leiomyoma than myometrium." (PMID 28930160, 2017). "An upregulated EGFR phosphorylation of Y845 in leiomyosarcomas compared to leiomyomas implicates EGFR activation at this special receptor site." (PMID 23449029, 2013). "It is also of interest that EGFR was only identified in the leiomyoma to leiomyoma comparison, while ERBB2 was identified only in leiomyoma compared to myometrium." (PMID 23785396, 2013). "Also, EGF activates DNA synthesis in leiomyoma, however EGFR demonstrates equally in both leiomyoma and myometrial smooth muscle cells." (PMID 41514933, 2026). "The role of EGFR phosphorylation has not been investigated so far in leiomyomas and leiomyosarcomas." (PMID 23449029, 2013). "Interestingly, in monolayer cultures of leiomyoma cells, progesterone was able to increase EGF but not EGFR expression; on the contrary, estrogens increased EGFR expression but did not increase EGF." (PMID 28930160, 2017).
Lewis lung carcinoma (9 papers, 2014 to 2023). "In animal experiments, C57BL/6J mice were subcutaneously injected with Lewis lung carcinoma cells stably expressing EGFR-Del19/T790M/C797S mutations to construct a xenograft model." (PMID 36744262, 2023). "In addition, self-immunization of mice using murine EGFR-ECD promoted not only a highly specific immune response but also a potent anti-metastatic effect in the EGFR+ Lewis lung carcinoma model." (PMID 28539888, 2017). "For example, a neutralising mouse anti-EGFR mAb, which alone displays anti-tumour activity in the Lewis Lung carcinoma model, could be added to the treatment regimen to radio-sensitise tumour cells as well as directly inhibit tumour growth." (PMID 24387284, 2014). "When these exosomes were incubated with mouse Lewis lung carcinoma (LLC) cells, a dose-dependent knockdown of EGFR expression was achieved, suggesting that the exosomal siRNAs were biologically functional." (PMID 33782530, 2021).
liver cirrhosis (9 papers, 2010 to 2025). "The expression of EGFR was remarkably higher in liver cirrhosis than in normal liver tissue." (PMID 36297027, 2022). "In our analysis, EGFR showed great impact in the PPI network-liver cirrhosis with a Degree of 149, Betweenness of 0.0245, and Closeness of 0.4498, which curcumin strongly interacts with and blocks its function with a low binding affinity energy of −8.9 kcal/mol." (PMID 36297027, 2022). "Epidermal growth factor (EGF)-EGF receptor (EGFR) signaling pathway plays key roles in both HCC and liver cirrhosis." (PMID 32322693, 2020). "The focal adhesion pathway encompasses several genes, and KEGG analysis demonstrated that AKT1, CTNNB1, EGFR, FN1, JUN, and SRC were strongly related to curcumin compounds that might be influenced by liver cirrhosis in our study." (PMID 36297027, 2022). "There was significant overexpression of EGFR and VEGF in HCC raised in the non-cirrhotic (virology negative) liver compared to those developed in post-hepatitic liver cirrhosis (p = 0.003 and p = 0.014)." (PMID 38414954, 2023). "EGFR and VEGF were overexpressed in HCC raised in the non-cirrhotic liver compared to those developed in post-hepatitic liver cirrhosis (p = 0.003 and p = 0.014)." (PMID 38414954, 2023). "HCC raised in the non-cirrhotic liver significantly overexpressed EGFR and VEGF in comparison to those developed in post-hepatitic liver cirrhosis." (PMID 38414954, 2023).
malignant mesothelioma (9 papers, 1990 to 2023). A malignant neoplasm of the pleura or peritoneum, arising from mesothelial cells. "A potential cancer type similar to NSCLC that might harbor functional EGFR mutations is malignant mesothelioma." (PMID 20942962, 2010). "In malignant mesothelioma, overexpression of the EGFR gene, which is detected by immunohistochemistry or FISH, is frequent, accounting for 44–90% of cases, and is probably caused by reactive oxygen species (ROS) present in the tumor microenvironment." (PMID 37046732, 2023). "ABX-EGF-BsAb specific for EGFR was used as a positive control, since malignant mesothelioma frequently shows over-expression of EGFR in either cell lines or the tumour itself." (PMID 29059207, 2017). "For example, maximal decreases in cell proliferation and invasion of malignant mesothelioma cells in vitro was observed by targeting c-Met and EGFR together." (PMID 21390244, 2010). "The expression of epidermal growth factor receptor (EGF-R) in 34 formalin fixed paraffin embedded specimens of malignant mesothelioma was examined using the F4 antibody." (PMID 2372497, 1990). "Epidermal growth factor receptor (EGFR) is highly overexpressed in malignant mesothelioma (MM)." (PMID 33023139, 2020). "While the epidermal growth factor receptor (EGFR)-dependent anti-proliferative and apoptotic effects of GA in malignant mesothelioma (SPC212) cells were demonstrated to be dually concentration- and time-dependent." (PMID 32028623, 2020).